NAT10 (N-acetyltransferase 10)
Diseases named in the same sentence as NAT10 in open-access papers (continued):
Sharing a sentence is not in itself a finding about the gene and the disease.
cancer (continued). "Therefore, targeting NAT10 may be useful for AML treatment approaches by promoting cancer cell apoptosis." (PMID 39817252, 2025). "Given the functional changes following NAT10 KD, Kyoto Encyclopedia of Genes and Genomes (KEGG) enrichment analysis of pathways was performed, highlighting pathways such as focal adhesion and gap junction, which are strongly associated with cancer cell migration and invasion." (PMID 40119353, 2025). "Therefore, targeting NAT10 has potential value for cancer treatment." (PMID 39817252, 2025). "Moreover, the functions of NAT10 have been found to differ according to the cancer type." (PMID 41310903, 2025). "Therefore, the therapeutic potential of NAT10 inhibitor Remodelin has been tested in many cancers." (PMID 39246323, 2024). "Reduced cell growth and proliferation are characteristic of NAT10-depleted cancer cells and could be related to the decrease of the formation of ac4C modification of FA metabolism-related genes caused by NAT10 depletion in these cells,which leads to the reduction of lipid levels." (PMID 38233930, 2024). "Therefore, our research indicated that the NAT10/NPM1 axis could be a promising target for cancer treatment." (PMID 38243170, 2024). "Thus, our results reveal that NAT10 plays a crucial role in cancer initiation and progression by modulating pri-miRNA ac4C to affect miRNA production, which would provide an attractive therapeutic strategy for cancers." (PMID 38308713, 2024). "In summary, we analyzed and integrated data from 488 COAD and 155 READ patients, 102 cancer cell lines, more than 15,000 immunostainings, and ∼10,000 raw associations between RBPs and cancer genes to unravel new RBPs involved in COAD (NOP56, NAT10, RBM12, and FKBP1A) and READ (EMG1 and CSE1L)." (PMID 37384253, 2023). "Since treatment of NAT10-depleted cancer cells with fer-1 reverses ferroptosis in cancer cells, we then asked whether the same condition is applicable in oxidative stress; therefore, we assessed mitochodrial membrane potential and cell ROS levels in NAT10-depleted cancer cells treated with fer-1." (PMID 37237981, 2023). "NAT10, as an epigenetic regulator, may aid in the treatment of cancer and osteoporosis." (PMID 36949954, 2023). "The discovery of ferroptosis among the highly modulated pathways from our previous RNA-seq in NAT10-depleted cancer cells led us to postulate that NAT10 depletion derails the expression of mRNAs belonging to key modulators of the ferroptosis pathway in cancer cells." (PMID 37237981, 2023). "Therefore, it is highly desirable to develop a NAT10-based drug for the treatment of cancer." (PMID 36553667, 2022). "Interestingly, NAT10 is overexpressed in 92% of cancer compared with normal tissues." (PMID 36149760, 2022). "Therefore, our study suggests that targeting NAT10 is a promising strategy for treating cancer." (PMID 36149760, 2022). "Whether NAT10 facilitates other important pathways in cancer cells is unknown." (PMID 36149760, 2022). "However, whether other crucial pathways are regulated by NAT10‐dependent ac4C modification in cancer cells remains unclear." (PMID 36149760, 2022). "Notably, many other enriched pathways were mitochondrial beta‐oxidation of long‐ and short‐chain FAs and FA elongation from mitochondria which were similarly identified in our previous study on metabolomic impact of Remodelin, a small molecular inhibitor of NAT10 on cancer cells." (PMID 36149760, 2022). "Therefore, the role of NAT10 in tumorigenesis and cancer progression may vary in different types of tumors." (PMID 28859621, 2017). "Our analysis revealed a significant upregulation of NAT10 expression in LUAD, a finding that was corroborated by investigations in both LUAD cancer tissue samples and cell lines." (PMID 41862454, 2026). "Collectively, these findingsposition NP1192 as a potent, selective NAT10-targeting PROTAC degradercapable of robustly depleting NAT10 protein and inhibiting ac4C modificationin cancer cells." (PMID 41341045, 2025).
cancer (continued). "PPAR signaling pathway has been previously reported to be regulated by NAT10 through ac4C modification of genes such as ELOVL6, ACSL1, ACSL3, ACSL4, ACADSB, and ACAT1, thus modulating fatty acid metabolism in cancer cells." (PMID 40123006, 2025). "This Khib modification stabilizes NAT10 protein by enhancing its interaction with deubiquitinase USP39 and then NAT10 increases NOTCH3 mRNA stability in ac4C manner, functionally contribute to cancer metastasis." (PMID 40164592, 2025). "During the temporal stage of tumorigenesis, the function of NAT10 may shift from protective (e.g., maintaining genomic stability in premalignant cells) to pro-oncogenic (e.g., driving proliferation and therapy resistance in established cancers) during disease progression." (PMID 41316475, 2025). "Future research should further investigate the role of NAT10 in the PC TME and explore its broader implications in cancer progression and immunotherapy." (PMID 41203621, 2025). "Therefore, this study suggests that NAT10 may exert a pro-cancer effect by modulating the nuclear factor erythroid-2, like-1(NFE2L1)-glutathione peroxidase-4(GPX4)signaling pathway in ccRCC, indicating its potential as a new therapeutic target for this malignancy." (PMID 41189569, 2025). "In summary, NAT10 plays a significant role in regulating EMT and cancer metastasis by influencing the expression of EMT‐related genes, modulating the cytoskeleton, and regulating the function of cell adhesion molecules." (PMID 39764566, 2025). "High mobility group box 2 (HMGB2) mRNA is ac4C‐modified by NAT10, and binding of eukaryotic translation elongation factor 2 (EEF2) to NAT10 increases HMGB2 expression and promotes cancer proliferation." (PMID 40448344, 2025). "Treating NAT10-depleted cancer cells with fer-1 increases cystine uptake in MCF7 and T47D cancer cells." (PMID 37237981, 2023). "These regulatory mechanisms shed light on the complex regulation of FSP1 in cancer, highlighting the involvement of NRF2, KEAP1, and NAT10 in modulating FSP1 expression and activity in the context of ferroptosis and therapeutic responses." (PMID 37371948, 2023). "The expression of NAT10 in 50 HCC tissues and corresponding adjacent tissues was evaluated using GEO database (GSE 7186), and the expression of NAT10 in cancer tissues was significantly upregulated (P < 0.0001)." (PMID 36765042, 2023). "Previous results showed that treatment of NAT10-depleted cancer cells with fer-1 reverses ferroptosis through assessment of cystine uptake and lipid ROS levels; therefore, we asked whether fer-1 could reverse the ferroptosis induced due to Remodelin treatment in cancer cells." (PMID 37237981, 2023). "The results showed that NAT10 and GLMP expression levels increased in normal, hyperplastic, and carcinoma tissues." (PMID 37914704, 2023). "N-acetyltransferase 10 (NAT10) catalyzes the acetylation of MORC2 at K767 and thus promotes DNA damage-induced G2 checkpoint arrest and decreases the sensitivity of cancer cell to DNA-damaging chemotherapy and radiotherapy." (PMID 35216622, 2022). "For example, the acetylation of MORC2 at K67 by NAT10 inhibit histone phosphorylation at H3T11 and induce the transcriptional repression of CDK1 and cyclinB1 to decreases the sensitivity of cancer cell to DNA-damaging chemotherapy and radiotherapy." (PMID 35216622, 2022). "Overall, these results show that the relationships of NAT10 expression with TMB and MSI are diverse in these five types of cancer." (PMID 34094911, 2021). "We assessed the correlation between the respective expression levels of NAT10 and OS, PFS, DFS, and DSS in different cancer types using a single-variate Cox regression analysis based on TCGA." (PMID 34094911, 2021). "Based on the potential of NAT10 as a therapeutic target in diseases such as cancer, HGPS and HIV, and the role of Remodelin as small molecule inhibitor of NAT10, we carried out virtual screening of FDA-approved drugs retrieved from Zinc database." (PMID 33723305, 2021).
cancer (continued). "Overall, in five types of cancer (ACC, HNSC, LIHC, KIRP and PCPG), NAT10 expression showed most relevant to immune infiltration levels." (PMID 34094911, 2021). "Overall, these results show that the relationships of NAT10 expression with TMB and MSI are diverse among these five types of cancer." (PMID 34094911, 2021). "In this study, a selective PROTAC degrader of NAT10, NP1192,isdesigned and proved to effectively reduce hypoxia-induced glycolysis,reverse CD8+ T cell dysfunction, and enhance anti-PD-L1therapy, making it a promising cancer immunotherapeutic agent." (PMID 41341045, 2025). "Overall, NAT10 drives HCC progression via SMAD3 mRNA stability regulation, and NAT10‐2023 could be a promising therapeutic candidate for targeting NAT10 in cancer treatment." (PMID 41476650, 2025). "Even under the same external conditions, spheroid formation of NAT10 KO U251 cells suggests that NAT10 contributes to the cancer stemness of GBM without being influenced by extracellular stimuli." (PMID 40288646, 2025). "In the last mechanism, NAT10 was identified as a facilitator of nucleophosmin (NPM1) acetylation, which enhances the transcription of PD-L1 and inhibits T-cell function in various types of cancer." (PMID 40588654, 2025). "In addition, NAT10 stabilizes KRT8 mRNA via ac4C acetylation, which drives cancer cell proliferation and metastasis." (PMID 41203621, 2025). "The role of NAT10 in cancer is gradually being revealed, although the role of NAT10-mediated RNA ac4C modification in ccRCC has not been reported." (PMID 40169553, 2025). "NAT10 also exerts its RNA acetyltransferase function and increases the ac4C modification of tRNA to eventually promote the viral yield and latency-to-lytic cycle transition of KSHV, a cancer-promoting herpesvirus." (PMID 40588654, 2025). "YAP is a target for certain types of post-transcriptional modification and plays important roles in cancer progression; however, whether YAP mRNA can be modified by NAT10-mediated ac4C still remains unknown." (PMID 38331765, 2024). "N-Acetyltransferase 10 (NAT10) is the only human mRNA ac4C modification enzyme with both acetyltransferase and RNA-binding activities and has been proven to be related to the development and prognosis of various cancers." (PMID 39246323, 2024). "The ac4C modification enhances HNRNPUL1 mRNA stability and upregulates its expression in CC.These findings contribute to our understanding of the NAT10-ac4C-HNRNPUL1 for tumorigenesis of CC, meanwhile it might be potential target forcervical cancer therapy." (PMID 37484809, 2023). "In bladder cancer, NAT10‐mediated reduction of ac4C modification was reported to suppress the stability and translational efficiency of BCL9L, SOX4 and AKT1, thereby inhibiting cancer progression." (PMID 36149760, 2022). "On the other hand, there is up- or down-regulation of specific factors that may interact with NAT10 or THUMPD1 and contribute to cancer development." (PMID 34762107, 2021). "Meanwhile, using OS, PFS, DFS, and DSS data from TCGA, we discovered that three of 33 cancers (ACC, KIRP, LIHC) showed consistent correlations between unfavorable prognosis wtih NAT10 expression; NAT10 expression in HNSC and PCPG showed significant correlations with OS, PFS, and DSS but not DFS." (PMID 34094911, 2021). "In addition, Remodelin was shown to weaken doxorubicin resistance and suppress hypoxia in cancer through NAT10/(VIM/TWIST/CDH1) and NAT10/(HIF1A/HIF2A) respectively." (PMID 33723305, 2021). "NAT10 has also been reported to regulate autophagy and pyroptosis, although not in cancers." (PMID 40588654, 2025). "Currently, the NAT10‐related molecular mechanisms in various cancers are not fully understood." (PMID 39817252, 2025). "Studies have reported the impact of targeting ferroptosis in cancer cells; however, no study has shown whether ferroptosis could be induced via NAT10-mediated acetylation." (PMID 37237981, 2023).
cancer (continued). "However, in our study, reverse transcription qRT-PCR showed that the difference in expression levels of NAT10 in cancer and normal tissues was not significant." (PMID 36339718, 2022). "In addition, NAT10 expression had significant correlations with infiltrating levels of B cells in 15 types of cancer, CD8+ T cells in 17 types of cancer, CD4+ T cells in 20 types of cancer, macrophages in 13 types of cancer, neutrophils in 23 types of cancer, and DCs in 19 types of cancer." (PMID 34094911, 2021). "However, as in the case of m6A RNA methylation regulators which change the levels of m6A in immune infiltration of cancers, the details of the molecular mechanism of NAT10 involved in the acetylation of mRNA are not clear." (PMID 34094911, 2021). "Although NAT10 and THUMPD1 work synergistically, their effects on prognosis of diverse cancer types are not totally the same." (PMID 34762107, 2021).
infection (8 papers, 2018 to 2025). The state of being infected such as from the introduction of a foreign agent such as serum, vaccine, antigenic substance or organism. "In this study, we established a PCV2-infected PK15 cell model and observed a marked downregulation of NAT10 expression following infection." (PMID 41472140, 2025). "A statistically significant decrease in NAT10 mRNA expression was observed at 24 h and 48 h post-infection compared to the control group (p < 0.01), as determined by qPCR assays, suggesting downregulation at the transcriptional level." (PMID 41472140, 2025). "As SINV regulates the NAT10 level during infection, the role of NAT10 in the SINV infection was investigated." (PMID 38169284, 2024). "The results of WB confirmed that infection with Over-NAT10 lentivirus produced effective overexpression of NAT10 in MSCs." (PMID 33953754, 2021). "In addition, the ac4C level on Gremlin 1 mRNA decreased after inhibition of NAT10 expression in MSCs and increased after infection with Over-NAT10 lentivirus." (PMID 33953754, 2021). "Notably, the RNA level of NAT10 increased as the multiplicity of infection (MOI) increased." (PMID 35971620, 2022). "In addition, among 46 TRP32 target genes previously found to be differentially expressed during infection, 8 are also TRP47 targets, including CAP1, CMC1, HLX, ING1, MTFR2, NAT10, PARP16, and POLDIP3." (PMID 30408047, 2018). "The NAT10 inhibitor remodelin could inhibit HIV-1 replication at concentrations without affecting cell viability, indicating that N4-acetylcytidine plays an essential role in infection with viruses and can regulate enterovirus 71 replication and virulence." (PMID 37484809, 2023). "Collectively, these findings suggest that the absence of NAT10 in B cells heightened the susceptibility of mice to H7N9 virus infection, as evidenced by enhanced viral propagation and inflammation induced by the influenza A virus in the early stages of infection." (PMID 40615576, 2025).
cardiac diseases (4 papers, 2024 to 2025). "In the field of cardiovascular disease, NAT10 has been shown to be associated with myocardial remodeling and vascular remodeling, however, the function of NAT10 in inflammation-associated cardiac diseases remains poorly studied." (PMID 40593466, 2025). "Therefore, the crucial involvement of NAT10‐mediated ac4C acetylation is significant in the cardiac fibrosis progression, affording promising molecular targets for the treatment of fibrosis and relevant cardiac diseases." (PMID 39482983, 2024). "It is worth noting that, NAT10 was also found playing a non-classic role in cardiac disease independent of the ac4C catalyzing activity." (PMID 40588654, 2025).
cardiovascular diseases (3 papers, 2025). "Understanding the mechanisms by which NAT10 influences macrophage behavior can inform the development of novel therapeutic strategies aimed at controlling excessive inflammation in human cardiovascular diseases." (PMID 40593466, 2025).
neurological diseases (3 papers, 2025). "Studies have shown that NAT10 protects against neurological diseases." (PMID 41446042, 2025). "NAT10 catalyzes the ac4C modification, a highly conserved RNA modification mechanism that regulates physiological and pathological processes in cardiovascular, immune, and neurological diseases." (PMID 41446042, 2025). "NAT10-mediated ac4C modification regulates Lipin1 expression, contributing to the pathogenesis of PWMI and offering potential therapeutic targets for preterm birth-related neurological disorders." (PMID 40779453, 2025).
infectious disease (2 papers, 2024 to 2025). A disorder directly resulting from the presence and activity of a microbial, viral, or parasitic agent in humans. "Remarkably, aberrant NAT10 and the ac4C levels also contributes to infectious diseases including HIV and influenza A virus infection." (PMID 38167491, 2024). "NAT10 and ac4C modifications are deemed to have crucial roles in infectious diseases." (PMID 40588654, 2025). "Moreover, NAT10 dysregulation is correlated with various types of tumors, infectious diseases and inflammatory diseases." (PMID 38167491, 2024).
hematological cancers (1 paper, 2022). "NAT10 is mostly investigated in solid cancers, but less in hematological cancers." (PMID 35978804, 2022).
neurodegenerative disease (1 paper, 2025). A disorder of the central nervous system characterized by gradual and progressive loss of neural tissue and neurologic function. "Recent studies have begun to elucidate the role of NAT10 (N-acetyltransferase 10)-mediated ac4C modifications in various physiological and pathological processes, particularly in neurodegenerative diseases." (PMID 40223095, 2025).
NAT10 also shares sentences with these, for which no sentence is quoted: triple-negative breast carcinoma (4 papers); anemia (3); diabetes (3); Anxiety (2); biliary tract cancer (2); brain tumor (2); cardiac hypertrophy (2); cardiac ischemia (2); hepatitis B (2); Hypoalbuminemia (2); kidney disease (2); lymphoma (2); lymphopenia (2); malnutrition (2); preeclampsia (2); sarcoma (2); sarcopenia (2); small cell lung carcinoma (2); acute kidney injury (1); acute pancreatitis (1); adenocarcinoma (1); adrenocortical carcinoma (1); AIDS (1); alcoholic liver diseases (1); Alzheimer disease (1); B-cell lymphoma (1); Cachexia (1); colon adenocarcinoma (1); Cri-du-chat syndrome (1); Cushing syndrome (1).
A further 48 diseases each share a sentence with NAT10 in 1 paper.